CHST1 (carbohydrate sulfotransferase 1)
Description:
Sulfotransferase that utilizes 3'-phospho-5'-adenylyl sulfate (PAPS) as sulfonate donor to catalyze the transfer of sulfate to position 6 of internal galactose (Gal) residues of keratan. Cooperates with B4GALT4 and B3GNT7 glycosyltransferases and CHST6 sulfotransferase to construct and elongate disulfated disaccharide unit [->3(6-sulfoGalbeta)1->4(6-sulfoGlcNAcbeta)1->] within keratan sulfate polymer. Has a preference for sulfating keratan sulfate, but it also transfers sulfate to the unsulfated polymer. Involved in biosynthesis of phosphacan, a major keratan sulfate proteoglycan in the developing brain (By similarity). Involved in biosynthesis of 6-sulfoGalbeta-containing O-linked glycans in high endothelial venules of lymph nodes. May act in a synergistic manner with CHST4 to generate sialyl 6',6-disulfo Lewis X motif, a recognition determinant for immune cell receptors implicated in leukocyte trafficking. Catalyzes sulfation of N-acetyllactosamine (LacNAc) oligosaccharides with highest efficiency for sialylated LacNAc structures.
Synonyms: GST-1; KS6ST; KSGal6ST; KSST; C6ST
Tractability: Antibody: UniProt predicts a signal peptide or a membrane-spanning region.
Gene: Protein-coding gene on chromosome 11 (45,647,689 to 45,666,096, reverse strand). Ensembl gene ENSG00000175264.
Subcellular location: Golgi apparatus membrane
Subcellular location (Human Protein Atlas): Mitochondria; Nucleoli
Pathways (Reactome):
Metabolism: Keratan sulfate biosynthesis
Gene Ontology:
Molecular function: keratan sulfotransferase activity; protein binding; sulfotransferase activity; N-acetylglucosamine 6-O-sulfotransferase activity
Biological process: galactose metabolic process; keratan sulfate proteoglycan biosynthetic process; sulfur compound metabolic process; keratan sulfate proteoglycan metabolic process; N-acetylglucosamine metabolic process; polysaccharide metabolic process; carbohydrate metabolic process
Cellular component: Golgi membrane; membrane
Genetic constraint (gnomAD): Loss-of-function variants: 13 observed, 29.71 expected, observed/expected ratio (o/e) 0.44, 90% interval 0.28 to 0.7. The upper end of that interval is the gene's LOEUF score, 0.7, which puts it in group 2 of 6, group 1 being the genes least tolerant of losing a copy. Missense variants: 439 observed, 567.78 expected, observed/expected ratio (o/e) 0.77, 90% interval 0.71 to 0.84. Synonymous variants: 267 observed, 263.86 expected, observed/expected ratio (o/e) 1.01, 90% interval 0.92 to 1.12.
Homologues: Orthologues: dog CHST1 (98% identical), pig CHST1 (98% identical), chimpanzee CHST1 (98% identical), macaque CHST1 (98% identical), guinea pig CHST1 (97% identical), rabbit CHST1 (96% identical), rat Chst1 (95% identical), mouse Chst1 (94% identical), tropical clawed frog chst1 (74% identical), zebrafish chst1 (73% identical), Drosophila melanogaster CG31637 (21% identical), Drosophila melanogaster CG9550 (17% identical). Paralogues in human: CHST3 (41% identical), CHST6 (31% identical), CHST2 (31% identical), CHST5 (30% identical), CHST4 (29% identical), CHST7 (29% identical).
Diseases named in the same sentence as CHST1 in open-access papers:
CHST1 is named in the same sentence as 15 diseases in open-access papers, as found by Europe PMC text mining. Sharing a sentence is not in itself a finding about the gene and the disease. The quoted sentences say what the papers report.
acute lymphoblastic leukemia (1 paper, 2018). Leukemia with an acute onset, characterized by the presence of lymphoblasts in the bone marrow and the peripheral blood. "Some of these genes have already been shown to play a role in hematologic malignancies, including CLL (Pim-2, Met, Rgs16, Ccdc88a, Zcchc18, Clip3), diffuse large B cell lymphoma, follicular lymphoma (Vav3), acute lymphoblastic leukemia (ALL) (Itm2a, Chst1) or acute myeloid leukemia (AML) (Chd3)." (PMID 30271400, 2018).
adenomyosis (1 paper, 2025). The growth of endometrial tissue inside the muscular wall of the uterine corpus. "At the molecular level, several enzymes involved in keratan sulfate biosynthesis were consistently upregulated in eutopic endometrium from adenomyosis patients, including B4GALT1, B3GNT2, CHST1, and CHST6." (PMID 41356013, 2025).
disc degeneration (1 paper, 2019). "Our results also showed that several enzymes that catalyze the biosynthesis of sulfated glycosaminoglycans (GAGs) of proteoglycans, including CHST1, EXTL3 and SLC26A2, were differentially methylated in the advanced stage of human disc degeneration compared to those in the early stage." (PMID 31513634, 2019).
gastric cancer (1 paper, 2020). A primary or metastatic malignant neoplasm involving the stomach. "NOX4 (logFC = 1.948, P = 4.55e-12), COL8A1 (logFC = 1.982, P = 1.22e-8) and CHST1 (logFC = 1.783, P = 9.04e-13) were significantly upregulated in gastric cancer tissues." (PMID 33193668, 2020). "In the cohort from the GEPIA database, the expression of NOX4, COL8A1, and CHST1 in gastric cancer tissues was higher than that in normal tissues, and the expression levels of NOX4 (F = 5.67 and P = 0.0008) and COL8A1 (F = 6.49 and P = 0.0003) differed across the four pathological stages." (PMID 33193668, 2020). "In addition, the expression of the target genes NOX4, COL8A1 and CHST1 in the brown module was upregulated in gastric cancer, and these genes could predict the prognosis of gastric cancer patients, as verified in 3 independent cohorts." (PMID 33193668, 2020).
ovarian clear cell cancer (1 paper, 2021). An invasive malignant neoplasm that arises from the ovary and is characterized by a predominance of clear and hobnail malignant epithelial cells. "During characterization of a monoclonal antibody HMOCC-1 against the ovarian clear cell cancer cell line RMG1, CHST1 was found to play a regulatory role in the formation of the sulfated glycan HMOCC-1 epitope." (PMID 34555499, 2021).
type 2 diabetes (1 paper, 2022). "The genes PPP2R2C and CHST1 have both been linked to the metabolic traits type 2 diabetes through GWAS studies." (PMID 35013117, 2022). "The validation analysis showed two statistically significant CpGs with the rank regression method related to two genes associated to metabolic traits, PPP2R2C and CHST1, which have been linked to the metabolic trait type 2 diabetes." (PMID 35013117, 2022).
tumor (7 papers, 2020 to 2025). "Tumor endothelial cells upregulated angiogenesis-associated genes including CHST1, FOLH1, and MMP1522–24." (PMID 38744958, 2024). "While some literature demonstrated that enhanced CHST1 was related to tumour development, its role in IVDD remains unexplored." (PMID 39636180, 2024). "Our TMA study showed that protein expression levels of sulfotransferases Gal3ST4 and CHST1 remained the same in serous ovarian tissue from all tumor stages and degree of differentiation, whereas Gal3ST2 levels were decreased in malignant tissue." (PMID 34555499, 2021). "Co-expressed genes and TIF miRNAs associated with tumor grade were BTRC, CHST1, miR-10a/b, miR-107, miR-301a, and miR-454." (PMID 32605588, 2020). "Another gene of interest in relation to tumor grade was CHST1 (carbohydrate sulfotransferase 1), which was paired with miRNAs miR-301a/b and miR-454." (PMID 32605588, 2020). "The expression of these three target genes is also positively correlated with the degree of immune cell infiltration in the gastric cancer tumor microenvironment, suggesting that NOX4, COL8A1 and CHST1 may be involved in the establishment of the tumor immune microenvironment." (PMID 33193668, 2020). "The literature on CHST1 and cancer is very limited; however, studies on other members of the carbohydrate sulfotransferase (CS) family show that while some CS members may be oncogenic, others could have tumor suppressor functions." (PMID 32605588, 2020).
cancer (5 papers, 2019 to 2025). A tumor composed of atypical neoplastic, often pleomorphic cells that invade other tissues. "We were unable to demonstrate clear functions for CHST1 as well as CHST3 in 6-O-sulfation of the cancer-associated Tn O-glycan." (PMID 34954141, 2022). "The expression of sulfotransferase CHST1 is related to the sensitivity of Siglec ligands to carbohydrate sulfation inhibition, and its high expression is generally associated with poor prognosis in specific cancers." (PMID 39867909, 2024).
adenocarcinoma (1 paper, 2013). A common cancer characterized by the presence of malignant glandular cells. "Of the 152 predicted gene targets in mouse and human genomes, four were significantly regulated in laser dissected lung dysplasia (AZIN1, CHST1, CRISPLD2 and FOXQ1) while 11 genes were significantly regulated in laser-dissected adenocarcinomas." (PMID 24265725, 2013).
CHST1 also shares sentences with these, for which no sentence is quoted: acute myeloid leukemia (1 paper); diffuse large B-cell lymphoma (1); follicular lymphoma (1); glioma (1); lung adenocarcinoma (1); mammary tumours (1).